SGK3 (serum/glucocorticoid regulated kinase family member 3)
Diseases named in the same sentence as SGK3 in open-access papers (continued):
Sharing a sentence is not in itself a finding about the gene and the disease.
tumor (continued). "Notably, the expression trends of KIAA0319, DERL1, SGK3, and CLTCL1 in tumor tissues mirrored those observed in the cell lines, providing consistency between in vitro and in vivo observations." (PMID 39792732, 2025). "Interesting, we also confirmed that knockdown of SGK3 could re-sensitize resistant cells to both BYL719 and inavolisib, enhancing the anti-tumor effect of alpelisib in vivo." (PMID 40303291, 2025). "Immunoblot analysis also revealed that SGK3 protein level was not markedly upregulated in tumours of mice treated with either Akt inhibitor (MK‐2206) alone or in combination with SGK3 inhibitor (14h)." (PMID 27481935, 2016). "Interestingly, we found that a subset of human HCC (20/52; 38.5%) exhibited higher SGK3 immunoreactivity in tumor when compared with the corresponding non-tumorous counterpart." (PMID 30975125, 2019). "Similarly, in human HCC cell lines, silencing of SGK3 reduced PIK3CA(E545K) -but not PIK3CA(H1047R)- induced accelerated tumor cell proliferation." (PMID 30975125, 2019). "INPP4B shRNA knockdown attenuated melanoma cell proliferation and xenograft tumour growth, whereas INPP4B overexpression enhanced cell proliferation and promoted melanocyte anchorage-independent cell growth, driven by INPP4B-mediated activation of SGK3 in an AKT-independent manner." (PMID 28082369, 2017). "We found that all tumor cells exhibited membranous E-cadherin staining, and Vimentin could only be found in stromal cells, but not HCC cells, of either Sgk3 wild-type or KO mice." (PMID 30975125, 2019). "However, it is not clear whether the reactivation was mediated through SGK3 phosphorylating TSC2 at Akt sites (Thr1462), since the tumour samples obtained from monotreated (MK‐2206) or combination (MK‐2206 and 14h) mice showed similar level of TSC2 phosphorylation." (PMID 27481935, 2016).
infection (3 papers, 2013 to 2022). The state of being infected such as from the introduction of a foreign agent such as serum, vaccine, antigenic substance or organism. "We had previously reported that PAN stimulation and SGK3 shRNA infection of podocytes significantly decreased the phosphorylation of GSK3β, and the SGK3/GSK3β signaling pathway inhibited podocin expression during PAN-induced podocyte injury." (PMID 35126185, 2021). "Of the 17 HPK genes identified important for A/WSN/33 replication, six (CDK13, HK2, NEK8, PANK4, PLK4, SGK3) emulated the phenotype following A/New Caledonia/20/99 infection, i.e. increased or decreased virus replication as measured by influenza NP localization and influenza M gene levels." (PMID 23805279, 2013). "Flow cytometry results show that siRNA silencing the expression of SGK3, ULK3, ERBB4, STK17B can reduce the infection efficiency of ORFV-GFP virus, while siRNA silencing the expression of MST1R, PAK4, ERBB3 can increase the infection of ORFV-GFP virus efficient." (PMID 35401439, 2022).
metabolic disease (2 papers, 2022 to 2025). A congenital disorder (due to inherited enzyme abnormality) or acquired (due to failure of a metabolically important organ) disorder resulting from an abnormal metabolic process. "The effects of SGK3 on the transport of glucose and amino acids can participate in the absorption of nutrients and is associated with a variety of metabolic diseases." (PMID 36531961, 2022).
nervous system diseases (1 paper, 2022). "In short, SGK3 can tune GluR1, GluR6, EAAT1, EAAT2, EAAT4, EAAT5, and SN1, participating in the transport of glutamate and glutamine in the nervous system, and play a role in the (patho) physiological process of various nervous system diseases." (PMID 36531961, 2022). "SGK3 can up-regulate GluR1, GluR6, EAAT1, EAAT2, EAAT4, EAAT5, and SLC38A3, participate in the transport of glutamate and glutamine in the nervous system, and play a role in (pathological) physiological process of various nervous system diseases." (PMID 36531961, 2022).
SGK3 also shares sentences with these, for which no sentence is quoted: acute myeloid leukemia (1 paper); cardiac insufficiency (1); cardiovascular diseases (1); Cirrhosis (1); cognitive deficits (1); diabetes (1); Huntington disease (1); malaria (1); ovarian tumor (1); overnutrition (1); pancreatic cancer (1); Proteinuria (1); renal failure (1).